LNCBRM (lncRNA SMARCA2 (BRM) associated)
Synonyms: LINCR-0003
Gene: Long non-coding RNA gene on chromosome 5 (57,574,027 to 57,629,629, forward strand). Ensembl gene ENSG00000249436.
Diseases named in the same sentence as LNCBRM in open-access papers:
LNCBRM is named in the same sentence as 2 diseases in open-access papers, as found by Europe PMC text mining. Sharing a sentence is not in itself a finding about the gene and the disease. The quoted sentences say what the papers report.
liver cancer (2 papers, 2016 to 2019). An epithelial or non-epithelial malignant neoplasm that arises from the liver. "LncBRM associates with BRM to initiate the BRG1/BRM switch and the BRG1-embedded BAF complex and triggers activation of YAP1 signaling, which maintains the self-renewal of liver cancer stem cells (CSCs) and promotes tumor initiation." (PMID 31582742, 2019).
tumor (2 papers, 2016 to 2019). "LncBRM was highly expressed in HCC primary tumour tissues through northern blotting and it was also highly transcribed in advanced HCC samples through quantitative reverse transcriptase–PCR (RT–qPCR), further validated by in situ hybridization." (PMID 27905400, 2016). "We observed that lncBRM overexpression augmented in vitro oncosphere formation and self-renewal, as well as promoted xenograft tumour propagation and tumorigenic cell frequency." (PMID 27905400, 2016). "LncBRM is required for the self-renewal maintenance of liver CSCs and tumour initiation." (PMID 27905400, 2016). "In summary, lncBRM is highly expressed in HCC tumours and liver CSCs, which triggers YAP1 signalling to promote self-renewal of liver CSCs and initiate tumour propagation." (PMID 27905400, 2016).